HMGB1 (high mobility group box 1)
Diseases named in the same sentence as HMGB1 in open-access papers (continued):
Sharing a sentence is not in itself a finding about the gene and the disease.
ischemic stroke (continued). "HMGB1, like in other inflammatory diseases, plays a central role in inflammation after ischemic stroke." (PMID 36232519, 2022). "In another study in 338 patients, plasma levels of HMGB-1 was an independent predictor of 1-year clinical outcomes of ischemic stroke." (PMID 35237675, 2022). "In our previous study, we also reported that anti-HMGB1 mAb therapy conferred protection in an ischemic stroke model in rats by protecting the BBB and inhibiting the associated inflammatory responses in the rat brain." (PMID 36230933, 2022). "After ischemic stroke, high mobility box 1 (HMGB1), peroxiredoxin (PRX), and heat shock proteins (HSP)—which are included in the DAMPs—induce neuroinflammation." (PMID 36671605, 2022). "Although the clinical value of HMGB1 has been confirmed in numerous diseases, studies focusing on the association of HMGB1 concentrations with SAP in patients with ischemic stroke have rarely been carried out." (PMID 36421903, 2022). "Taken together, these results convey a novel concept that HT induced by delayed t-PA is mediated by the peroxynitrite/HMGB1/MMPs signaling pathway in ischemic stroke." (PMID 35457061, 2022). "It has also been shown that the level of HMGB1 circulating in blood was positively correlated with the severity and infarct volume in patients with ischaemic stroke." (PMID 34231932, 2021). "For instance, antibody-mediated neutralization of HMGB1 or its antagonism via HMGB1 box A or glycyrrhizin can be neuroprotective in ischemic stroke models." (PMID 34572077, 2021). "In ischemic stroke, high mobility group box 1 (HMGB1) and the peroxiredoxins (PRXs) have been identified as the DAMPs." (PMID 34014921, 2021). "Our previous study demonstrated that therapeutic application of TTM helps alleviate peri-infarct damage from the propagation of ischemic injury in an ischemic stroke model by reducing inflammatory cytokines through the blockage of HMGB1 release." (PMID 33503060, 2021). "In ischemic stroke, increased concentration of HMGB1 in circulation happened within hours after tissue damage." (PMID 32994992, 2020). "In the early phase of ischemic stroke, neurons die, and subsequently, HMGB1 is released from the neurons for accelerating the inflammatory response." (PMID 33287126, 2020). "There is some evidence to suggest that ischemic stroke postprocessing forms a two-way feedback mechanism to protect the brain, restraining autophagy and reducing the secretion of HMGB1." (PMID 31001089, 2019). "Studies have demonstrated that HMGB1 is involved in the pathogenesis of ischemic stroke in adult rodents, activating microglia and promoting neuroinflammation." (PMID 31920543, 2019). "The second peak of HMGB1 after ischemic stroke, however, is thought to be secreted by various immune cells such as microglia, macrophages, astrocytes, and vascular endothelial cells." (PMID 31001089, 2019). "Clinically, HMGB1 were found to be significantly higher in serum or plasma of patients with ischemic stroke when compared to age- and sex-matched controls." (PMID 31291966, 2019). "Studies have shown that HMGB1 is involved in the pathogenesis of ischemic stroke and reperfusion injury." (PMID 31001089, 2019). "Various studies have demonstrated that blocking or modulating HMGB1 by compounds such as statins (atorvastatin, fluvastatin) and by shRNA provided neuroprotective effects against ischemic stroke." (PMID 31291966, 2019). "When an ischemic stroke occurs, HMGB1 is released into peripheral blood from the central nervous system (CNS)." (PMID 31001089, 2019). "Here, we firstly demonstrate that HMGB1 blocking peptide reduced the tPA-associated mortality, brain hemorrhage, swelling, and BBB disruption in an animal model of ischemic stroke." (PMID 30139371, 2018). "Emerging evidence suggests that the multiligand receptor for advanced glycation end products (RAGE) and its ligand high mobility group box 1 protein (HMGB1) contribute to the pathophysiology of ischaemic stroke (IS)." (PMID 29245967, 2017).
ischemic stroke (continued). "In patients with ischemic stroke, increased plasma levels of MMP9 and HMGB1 are associated with a poor functional outcome and are significantly correlated with each other." (PMID 28348451, 2017). "Further clinical studies are needed for development of a new treatment strategy to inhibit the HMGB1 pathway, thus preventing the inflammation in ischemic stroke patients." (PMID 27040385, 2016). "In this regard, the purpose of this study was to assess the expression level of TLR2 on monocytes in patients with ischemic stroke and to evaluate the expression change profile following high-mobility group box 1 (HMGB1) stimulation." (PMID 27040385, 2016). "Our results also suggest that HMGB1 inhibitors are worth being assessed for their ability to act as neuroprotectants in human ischemic stroke." (PMID 27544687, 2016). "We also confirmed that ischemic stroke leads to more severe brain injury in diabetic mice than non-diabetic mice, and that inflammation and brain injury can be ameliorated by blocking HMGB1 function with neutralizing antibodies." (PMID 27596007, 2016). "Our data establish that IVIg targets expression and activation of TLR and RAGE pathway components as well as protecting neurons against HMGB1-mediated neuronal cell death in ischemic stroke." (PMID 25886362, 2015). "Our results indicate that forced expression of HDAC4 and HDAC5 decreases not only HMGB1 release but also expression, indicating the contributing role of HDAC4 and HDAC5 on the regulation of HMGB1 function in ischaemic stroke." (PMID 23480850, 2013). "In ischemic stroke and intracerebral hemorrhage especially, extracellular HMGB1 is suggested to exacerbate brain insult through the disruption of the blood-brain barrier (BBB), overfacilitation of microglia, and intense production of proinflammatory molecules." (PMID 22645697, 2012). "Intravenous injection of neutralizing anti-HMGB1 monoclonal antibody has been suggested as a novel therapeutic strategy for ischemic stroke." (PMID 22277256, 2012). "In an ischemic stroke animal model, the serum level of HMGB1 increased 4 hours after ischemia, and HMGB1 was massively released into the extracellular space immediately after ischemic insult." (PMID 21982558, 2011). "In patients with ischemic stroke, the serum or plasma levels of HMGB1 are dramatically higher than those in age- and gender-matched controls." (PMID 21982558, 2011). "Notably, recent studies have revealed that berberine’s regulatory effect on HMGB1 is associated with lncRNA Malat1, where lncRNA Malat1 competitively binds miR-181c-5p - a direct HMGB1 target - to regulate HMGB1 expression following ischemic stroke." (PMID 40756985, 2025). "However, it is important to note that HMGB1 exhibits a complex biphasic role in the pathogenesis and progression of ischemic stroke." (PMID 40066310, 2025). "HMGB1-targeted therapy improves the prognosis of ischemic stroke." (PMID 38740617, 2025). "However, given the complex role of HMGB1 at different times of ischemic stroke, the time window for targeting HMGB1 therapeutic modalities needs to be further investigated." (PMID 38740617, 2025). "Physical therapies after ischemic stroke include remote Ischemic preconditioning, hyperbaric oxygen, and hypothermia treatment, which may be involved in inhibiting HMGB1-mediated ischemic brain injury." (PMID 38740617, 2025). "In addition to the internalized clearance of HMGB1, autophagy as a critical process for immune regulation in ischemic stroke needs to be further studied." (PMID 38740617, 2025). "HMGB1 may promote ischemic stroke progression during the acute phase through excitatory amino acid toxicity, oxidative/nitrification stress, and modulation of neuroinflammation." (PMID 38740617, 2025). "HMGB1 plays a role in the dual action of astrocytes in ischemic stroke." (PMID 38740617, 2025).
ischemic stroke (continued). "Furthermore, we have summarized therapeutic strategies targeting HMGB1, aiming to establish HMGB1 as a novel target for the treatment and prognostic prediction of ischemic stroke and hemorrhagic transformation." (PMID 38740617, 2025). "Medicinal herbs may be a new possibility for the treatment of ischemic stroke, and HMGB1 targeting may be an essential mechanism involved." (PMID 38740617, 2025). "HMGB1 plays complex and biphasic roles in the onset and progression of ischemic stroke." (PMID 38740617, 2025). "Reducing HMGB1 expression may be important for suppressing the inflammatory response in ischemic stroke." (PMID 40128654, 2025). "Similarly, GA reduces apoptosis in ischemic stroke by preventing HMGB1-induced excitotoxicity and inflammation." (PMID 39598404, 2024). "In the setting of ischemic stroke, HMGB1 has been shown to interact with various pattern recognition receptors, such as Toll-like receptors (TLRs) and the receptor for advanced glycation end products (RAGE), leading to the activation of inflammatory signaling pathways." (PMID 38708343, 2024). "Circulating levels of HMGB1 could potentially serve as a prognostic indicator for the onset of cognitive impairment following ischemic stroke." (PMID 38708343, 2024). "Studying the effect of different redox modified HMGB1 on ischemic stroke may be an important topic of research." (PMID 37062906, 2023). "Currently, a few studies have explored the redox modification of HMGB1 after ischemic stroke." (PMID 37062906, 2023). "RAGE expressed on microglia could mediate the neurotoxicity of HMGB1 in an animal model of ischemic stroke." (PMID 36483598, 2022). "Importantly, this reduction in plasma HMGB1 was associated with reduced plasma NET levels (141.5% ± 38.1% vs. 233.7% ± 55.5%) and greatly improved ischemic stroke outcomes." (PMID 35358095, 2022). "Treatment with BoxA significantly reduced plasma MPO-DNA complexes (144.8% ± 56.2% vs. 275.4% ± 52.5%) and improved ischemic stroke outcomes (53.9 ± 26.7 mm3 vs. 88.2 ± 35.2 mm3), confirming a key role for HMGB1 mediating detrimental NET formation in ischemic stroke." (PMID 35358095, 2022). "The knockdown of HMGB1 in the brain may be an effective anti-inflammatory strategy to improve ischemic stroke." (PMID 39698442, 2022). "HMGB1 is released from necrotic neurons or is actively secreted from microglia, monocytes/macrophages, and neutrophils, mediating the neuroinflammatory response and contributing to the pathogenesis of ischemic stroke." (PMID 35203690, 2022). "In addition, a meta-analysis showed that ischemic stroke patients possessed elevated levels of HMGB1 compared with healthy controls, and the levels of HMGB1 were positively associated with severity and infarct volume in ischemic stroke patients." (PMID 36421903, 2022). "During ischemic stroke (IS), HMGB1 may signal through its possible receptors, such as RAGE, toll-like receptors (TLRs), and matrix metalloproteinases (MMPs)." (PMID 36388178, 2022). "HMGB1 has been found to be associated with the release of pro-inflammatory cytokines such as IL-1β, TNF-α, IFN-γ, and IL-6, and the activation of NF-κB and inflammasome activation after experimental ischemic stroke." (PMID 36232519, 2022). "Furthermore, HMGB1 predominantly localized at the interface of platelets interacting with neutrophils in ischemic stroke thrombi." (PMID 35358095, 2022). "Exosomes were utilized for HMGB1-siRNA delivery for treatment of ischemic stroke." (PMID 33869170, 2021). "Notably, recent research found that plasma levels of HMGB1 significantly increased in tPA-treated ischemic stroke patients, and HMGB1-triggered neuroinflammation aggravated tPA-mediated HT in a rat model of ischemic stroke." (PMID 34162400, 2021). "Interestingly, ameliorating the HMGB1-RAGE interaction via administering a decoy soluble RAGE receptor was found to be neuroprotective in ischemic stroke model." (PMID 34572077, 2021).
ischemic stroke (continued). "HMGB1 levels significantly increased in tPA-treated ischemic stroke patients and tMCAO rats." (PMID 34162400, 2021). "HMGB1, as a NETosis inducer in the ischemic brain, contributes to NETosis-mediated neuronal death and aggravates inflammation and subsequent brain tissue damage in ischemic stroke." (PMID 33384585, 2020). "HMGB1 is an important mediator during and after ischemic stroke." (PMID 33287126, 2020). "Moreover, different redox forms of HMGB1 in patients with ischemic stroke have unclear biological functions in the perpetuation and regression of inflammation after acute ischemic brain injury." (PMID 33384585, 2020). "HMGB1 is reported to be highly expressed in the blood not only during the acute phase but also for at least 2 weeks following ischemia in rats, even longer to around 1 month in ischemic stroke patients." (PMID 31001089, 2019). "Here, we summarize and review the research into HMGB1 in ischemic stroke." (PMID 31001089, 2019). "Hence, similar to other inflammatory mediators, HMGB1 plays an important role in aggravating detrimental events during ischemic stroke." (PMID 31291966, 2019). "During the advanced stages of ischemic stroke, the function of HMGB1 is not fully understood." (PMID 31001089, 2019). "It is believed that HMGB1 may be related to lymphopenia and immune-function failure after ischemic stroke." (PMID 31001089, 2019). "The results indicated that the potent anti-inflammatory effects of the dual-targeting nanoformulation against ischemic stroke might attribute to its blockade of HMGB1/TLRs/MyD88/TRIF/NF-κB signaling pathways." (PMID 35518053, 2019). "We hypothesize that CORM-3 might reduce the release of damage-associated molecular pattern molecules (DAMPs), such as high-mobility group box 1 (HMGB1) and galectin-3 (Gal3), which have been shown to stimulate microglia after ischemic stroke." (PMID 29929562, 2018). "The pro-inflammatory effect of Prxs, especially Prx5/6, is stronger than HMGB1 in ischemic stroke." (PMID 29554978, 2018). "Our findings indicate that HMGB1-mediated inflammation and BBB breakdown may contribute to tPA-induced occurrence of HT and death in ischemic stroke, and that blocking HMGB1 signaling would be helpful to prevent the complications brought by thrombolysis." (PMID 30139371, 2018). "Further study are warranted to determine whether the anti-inflammation of BCP on ischemic stroke through impairing HMGB1 release from necroptotic cells." (PMID 29123466, 2017). "Thus, our results reveal a previously uncharacterized property of HMGB1/IL-6 signaling pathway in EE-mediated angiogenesis and functional recovery after ischemic stroke." (PMID 28845299, 2017). "One aim of our study is to investigate whether HMGB1 is an important mediator of EE on angiogenesis and long-term functional recovery after ischemic stroke." (PMID 28845299, 2017). "The injection of neutralizing anti-HMGB1 antibodies alleviated brain injury and may represent a promising therapeutic approach for ischemic stroke in DM patients." (PMID 27596007, 2016). "Here we present evidence using a rat middle cerebral artery occlusion (MCAO) model of ischemic stroke that hypothermia inhibits infarct volume expansion by preventing HMGB1 release from post-ischemic neurons and diminishes subsequent inflammatory responses in the peri-infarct region." (PMID 27544687, 2016). "In addition, the elevated levels of IL-17, IL-33 and IL-6 were found in the plasma of patients with ischemic stroke, as well as in the supernatants of the cell monocyte stimulated by HMGB1." (PMID 27040385, 2016). "In addition, HMGB1 (high-mobility group protein B1), released by injured endothelial and other cells following ischemic stroke, activates TLR2/4 which leads to ROS generation and cytokine production." (PMID 25036109, 2014).
ischemic stroke (continued). "A number of interconnected pathways previously associated with ischemic stroke were over-represented in females, including TLR (Toll-like receptor), HMGB1, TREM1, PPARα/RXRα, Hypoxia, Renin-Angiotensin, Mitochondrial Dysfunction, Glucocorticoid receptor and cytokine signaling pathways." (PMID 25036109, 2014). "HMGB1 is expressed in the nucleus in normal conditions and rapidly translocates to the cytoplasm and release (or secrete) from dying cells into extracellular milieu in the setting of ischaemic stroke." (PMID 23480850, 2013). "Mechanistically, the anti-neuroinflammatory effects of SAD in ischemic stroke may be attributed to its inhibitory action on high mobility group box 1 (HMGB1) nuclear-to-cytoplasmic translocation and subsequent blockade of the TLR4/MyD88/NF-κB signaling cascade activation." (PMID 40756985, 2025). "However, unlike ischemic stroke, we did not detect meaningful HMGB1 variants with a possible link to IAs." (PMID 39451983, 2024). "Thus, HMGB1 released after ischemic stroke promotes excitatory amino acid toxic effects." (PMID 37062906, 2023). "However, the precise role of HMGB1 in ischemic stroke remains to be elucidated." (PMID 37062906, 2023). "Furthermore, HMGB1 levels predict reperfusion injury in ischemic stroke patients." (PMID 35358095, 2022). "Hence, ischemic stroke deficits could potentially be attenuated with the anti-HMGB1 mAb, as demonstrated by the antibody’s ability to remove HMGB1, stymie brain edema, and safeguard the BBB." (PMID 29786644, 2018). "Notably, it has been reported that HMGB1 released from damaged tissue may function as an endogenous agonist of TLR4 that aggravates ischemic brain damage in an ischemic stroke model." (PMID 28646881, 2017). "Notably, in our previous study of human peripheral blood leukocytes following ischemic stroke, we also observed sexually dimorphic cell death pathways with females showing Caspase 1, HMGB1, and NFkB Signaling pathways, while in males Granzyme A signaling and other cell death molecules were involved." (PMID 25036109, 2014). "In an in vitro study in a mouse model of ischaemic stroke, HBO was observed to inhibit HMGB1 via SIRT1-dependent deacetylation." (PMID 40243713, 2025). "We aimed to investigate the relationship between HMGB1 and BCP in in vivo and in vitro ischemic stroke models." (PMID 40128654, 2025). "Significant gaps remain in our understanding of the effect of HMGB1-RAGE axis-activated macrophages on neuroinflammation and neural focal death after ischemic stroke." (PMID 38740617, 2025). "From day 3 post ischemic stroke, MSR1-expressing macrophages increased, scavenging HMGB1 and PRX until 1 week post ischemic stroke." (PMID 36671605, 2022). "In a mouse model of ischemic stroke, we subsequently confirmed platelets as a critical source of HMGB1 during ischemic stroke brain injury and established that HMGB1-mediated NET formation exacerbates ischemic stroke outcomes." (PMID 35358095, 2022). "Results indicate that exosomes combined with HMGB1-siRNA decreased HMGB1, TNF-α, apoptosis, and infract volume, showing potential for recovery of ischemic stroke." (PMID 33869170, 2021). "For instance, angiotensin receptor blockers, such as telmisartan, irbesartan, and candesartan, can regulate the HMGB1-RAGE axis and inhibit RAGE expression, which exert a beneficial effect on prevention and treatment of ischemic stroke." (PMID 33384585, 2020). "Recently, it has been reported that HMGB1 works as an immune system signal (or DAMP), and that HMGB1 inhibition has a protective effect against damage following an ischemic stroke." (PMID 31001089, 2019). "The aim of this study was to assess the effects of HMGB1 on the TLR2 pathway and Th17 cell infiltration in patients with ischemic stroke." (PMID 27040385, 2016).